CD4 (CD4 molecule)
Diseases named in the same sentence as CD4 in open-access papers (continued):
Sharing a sentence is not in itself a finding about the gene and the disease.
tumor (continued). "The NDV-MIP3α-induced production of tumor-specific cellular and humoral immune responses was dependent on CD8+ T cells and partially on CD4+ T cells." (PMID 32759233, 2020). "As expected, PDL1 blockade favored tumor infiltration by CD45+ leukocytes, mainly composed of a higher fraction of CD4+ and CD8+ T cells also harboring a more pronounced activated state as depicted by intracellular IFNgamma staining." (PMID 32194552, 2020). "Tumor‐draining lymph nodes from intratumorally 17D‐treated mice were larger, reflecting an increase in the content of CD8, conventional CD4 cells, NK cells, and to a lesser extent, Tregs (Fig EV4A), resulting in an increase in the Tconv/Treg ratio (Fig EV4B)." (PMID 31746149, 2020). "The expression of PD-L1 and CD3+, CD4+, CD8+ tumor infiltrating lymphocytes (TILs) was detected by immunohistochemistry and the association between TILs, chemotherapy response, clinical outcome and PD-L1 expression was evaluated." (PMID 32493336, 2020). "An increase in TCF1+ CD4+ and CD8+ tumor-infiltrating lymphocyte (TIL) was indeed observed, but only in regressor tumors and significantly so in the case of the CD4+ T cell population." (PMID 33093155, 2020). "IFN-γ, as a typical Th1 cytokine, plays a vital role in the Anti-Tumor activities; therefore, we assessed the expression of SP-specific IFN-γ in CD4+ T and CD8+ T cells isolated from DTT-SP4- or DTSP-immunized mice after re-stimulation with SP in vitro." (PMID 32903495, 2020). "While TH1 CD4+ TIL are considered to augment cancer immunity, the roles of TH2 and TH17 are more nuanced and their involvement in tumor development and progression are not fully understood." (PMID 33013886, 2020). "Treg, defined as CD4+ CD25+ Foxp3+ T cell, is capable of immunosuppression which helps tumor cells escape from the immune system, accounting for poor prognosis in a variety of solid malignancies." (PMID 32685487, 2020). "These peculiar dynamics can be related to the need for rapid tumor de-bulking at early phases, provided by CD8+ CAR T cells, followed by the need for CD4+ CAR T cell help to achieve long-term anti-tumor control." (PMID 32636841, 2020). "We assessed the expression and activation of IL-2 signaling pathway components in CD4+ TILs and dLN cells in the MCA205 tumor model." (PMID 31924474, 2020). "In general, the more CD4+ or CD8+ T cells in the tumor mass, the better the tumor will respond to ICB treatment." (PMID 32566127, 2020). "On days 7 and 14 after radiation, the expression levels of CD86+, CD4+, CD8+, and Foxp3+ cells, and levels of Ki-67+ protein were detected by immunohistochemistry, and the tumor necrosis rate was calculated." (PMID 32942998, 2020). "Loss of host-derived MIF resulted in a decrease in intrasplenic and intratumoral Tregs following tumor inoculation and this corresponded with an increase in splenic CD4+ and CD8+ T cells and a decrease in tumor outgrowth." (PMID 33324425, 2020). "This analysis showed that CD38 was significantly correlated with tumor purity, CD8+ T cells, CD4+ T cells, and B cells in EOC." (PMID 32425977, 2020). "Among them, activated CD4 T memory cells were positively correlated with SPC25 expression; two kinds of tumor-infiltrating immune cells were negatively correlated with SPC25 expression, including regulatory T cells (Tregs), and resting memory CD4 + T cells." (PMID 32742802, 2020). "Antigen-specific IL9-secreting CD4 Th9 and CD8 Tc9 cells have been previously characterized for their anti-tumour properties." (PMID 33214555, 2020). "Using real-time PCR, we observed an upregulation of Bcl6 transcripts in tumor infiltrating Treg cells when compared with dLNs derived Treg cells (TdLN Treg) and CD44–CD4+ T cells (naive CD4)." (PMID 32477338, 2020). "To confirm the role of T cells in controlling tumor growth in this model, we depleted CD4+ and CD8+ T cells in tumor-bearing mice using an established protocol." (PMID 32528880, 2020).
tumor (continued). "Tumor tissues with high LINC02195 expression exhibited more infiltrating CD8+ and CD4+ T cells than tumor tissues with low LINC02195 expression." (PMID 32435615, 2020). "Finally, ~20% of the tumor-Treg β-CDR3s were shared with Tconv cells, pointing out that an important fraction of the Tregs could arise through peripheral induction or conversion of CD4+ Tconv cells." (PMID 32601304, 2020). "Again, the most frequent immune targets in CD4+ T cells from patients with GBM, in descending order, isolated from the tumor microenvironment were A2aR > PD-1 > CTLA-4 > CD39 > TIGIT > FOXP3 > LAG-3 > CD160 > TIM3 > KIR > CD73." (PMID 32721947, 2020). "This was supported by further studies, as deletion of GARP in mice led to an increase in CD4+ and CD8+ T cell anti-tumor activity." (PMID 33291452, 2020). "Activation of CD4+ T cells is essential for optimal CD8+ T cell priming, by enhancing antigen presentation and favoring cross‐priming of tumor antigen by DC137." (PMID 32594569, 2020). "Compared to those in the PBMCs, the ratios of exhausted CD4+ T cells and CD8+ T cells were distinctly higher at the AG tumor lesions." (PMID 33614475, 2020). "PD-L1 positivity of the tumor was correlated to a high amount of CD3 + (p = 0.047), CD4 + (p = 0.021), CD8 + (p = 0.038) and PD1 + (p = 0.014) TILs; Furthermore, a correlation was found between PD1 + TILs and comorbidity." (PMID 31980916, 2020). "Macrophages were the most abundant immune cell-type in the tumor microenvironment followed by CD8 + and CD4 + T-cells and both antigen presenting cells and neutrophils were more abundant in chemo-exposed samples." (PMID 32193378, 2020). "Especially CD4+ T cells showed a significant upregulation of galectin-9, whereas galectin-9 expression on CD8+ T cells increased only minimally within the tumor." (PMID 32055023, 2020). "In this study, we stained pretherapeutic biopsy samples with immunohistochemistry (CD4 and CD8) and examined intratumoral periglandular lymphocytes (IPLs) and TILs in relation to post-treatment tumor regression grade (TRG)." (PMID 33442477, 2020). "The PCNs increased the number of cytotoxic CD8+ T lymphocytes and CD68+iNOS+ M1-like macrophages, induced minimal changes in CD4+ T lymphocytes, and decreased CD68+/Arg-1+ M2-like macrophages in tumor tissues." (PMID 32928251, 2020). "Conversely, CD4+ TH2 cells and Tregs suppress the immune response and contribute to the inhibition of anti-tumor activity." (PMID 32751163, 2020). "In murine hepatocellular carcinoma, tumor-derived IL-33 promoted the expansion of IFN-γ+ CD4+ and CD8+ T cells, increased CTL cytotoxicity and inhibited tumor growth." (PMID 33329534, 2020). "An increased expression of CX3CL1 in a cancer cell leads to the infiltration of NK cells, dendritic cells, CD4+ and CD8+ T cells into the tumor." (PMID 32466280, 2020). "Another actionable co-inhibitory molecule is natural killer group 2 member A (NKG2A), which together with its co-receptor CD94 is expressed by many of the tumor-infiltrating CD8+ T cells and only by a minority of the CD4+ T cells in OPSCC." (PMID 33425717, 2020). "Accordingly, the evaluation of tumor growth kinetics, higher in the HPD group, correlated with a greater presence of this CD4+ subpopulation." (PMID 33168050, 2020). "Anti-CD19 CAR T cells generated from CD4+ TN and TCM cells exhibited a higher expression of CD62L and had favorable effects on survival of tumor-bearing mice compared to treatment with CAR T cells generated from CD4+ TEM." (PMID 32504246, 2020). "A histological examination revealed fibrosis and tumour cell death with an infiltration of CD8+ and CD4+ T-cells around tumour islets, supporting the induction of an immune response." (PMID 33574894, 2020). "We analyzed the status of central immune activity using immunophenotyping of splenocytes (CD45+, CD8+, and CD4+ cell counting) and observed similar levels of CD45+ cells in all groups, suggesting immune activated statuses against tumor cells." (PMID 32575351, 2020).
tumor (continued). "Compared to those in PBMCs, the proportions of TIM-3+ CD4+ T cells (p < 0.05) and PD-1+ CD8+ T cells (p < 0.01) were remarkably higher in tumor sites." (PMID 32117733, 2020). "DCs combined with antigens from a tumor or virus produce major histocompatibility complex (MHC) class I and II peptides epitopes to CD8 and CD4 T lymphocytes." (PMID 33363088, 2020). "However, we found that the proportion of CD8+ T cells were significantly decreased despite of increase of DC and CD4+ T cells in tumor after TLR9 agonist stimulation, suggesting that TLR9 agonist may induce immune escape by inhibiting T cell infiltration and activation in tumor microenvironment." (PMID 32483468, 2020). "Analysis of cellular characteristics showed that tumour-related macrophages were the most abundant TME-infiltrating cells, followed by CD4-positive T cells, and plasma cells." (PMID 32228629, 2020). "Generally, the number of CD4+ lymphocytes is lower than that of CD8+ lymphocytes in a GBM environment, but it has been observed that the numbers of both CD4+ and CD8+ cells increase with tumor grade." (PMID 33659213, 2020). "LAG3 belongs to the immunoglobulin superfamily (IgSF) and is particularly displayed on several forms of T-lymphocytes (CD4+, CD8+, regulatory T-cells [Treg], tumour infiltrating lymphocytes [TILs]), as well as B-lymphocytes and dendritic cells." (PMID 32592066, 2020). "MicroRNA miR-138 was suggested to function as a tumour suppressor and demonstrated to target CTLA-4 and programmed cell death 1 (PD-1) in CD4+T cells." (PMID 32054041, 2020). "Both CD4+ and CD8+ Temra clusters represent a small proportion of tumor‐infiltrating T cells in various cancer types." (PMID 32272497, 2020). "The antitumoral T cells, both CD4 and particularly the cytotoxic CD8 T cells, which can kill tumor cells, were unaffected by the siJnk2-LNP." (PMID 32393755, 2020). "To explore the correlation between various tumor immunity cell activities, we found that different TIIC subpopulations were weakly to moderately correlated, specially for T cell CD4 memory activated and T cell CD8." (PMID 32596334, 2020). "A high infiltrate of T cells, including CD3+, CD4+, and CD8+ T cells, in the tumour corresponds to increases in disease free survival and overall survival in CRC patients." (PMID 33292783, 2020). "T cells are the major component of the adaptive immune system consisting of CD4 and CD8 T cells, being the latter key players in the physical elimination of tumor and virus-infected cells." (PMID 32714330, 2020). "In human studies, tumor-infiltrating lymphocytes consist of both effector CD8+ T cells and CD4+ T cells, including regulatory T cells (Treg)." (PMID 33008010, 2020). "In this review, we discuss CD4 T cell responses against telomerase reverse transcriptase (TERT), a ubiquitous tumor antigen." (PMID 32630460, 2020). "As infiltrating T helper cells, specifically IFN-γ producing CD4+ Th1 cells, usually possess an anti-tumorigenic role in the TME, their elimination in the treated tumor due to chemotherapy supports pro-tumorigenic activity." (PMID 33276524, 2020). "At first, only CD4+/CD8+ T cells engineered with AsNRs were i.v. injected; however, we found that, in the presence of engineered cells alone, the tumor cells were difficult to kill, and the treatment had unsatisfactory results." (PMID 32358530, 2020). "Within the TME, there is a similar trend of increased effector cells (CD4+ and CD8+ T cells and NK cells) and a reduction in pro-tumor immune suppressors (MDSCs and Tregs) in animals exposed to PA interventions." (PMID 33134306, 2020). "The results were promising as a significant reduction in tumor size was accompanied by an increase in the infiltration of mTrop2‐specific CD8+ T cells, CD4+ T cells as well as natural killer cells." (PMID 31456339, 2020).
tumor (continued). "The main site of tumor growth in MM is the bone marrow, therefore we evaluated the frequency of PD-1+ or TIM-3+ subsets of CD4+ and CD8+ T cells in BM samples obtained from MM patients." (PMID 33257767, 2020). "CD4+T and CD8+T cells assume tumor immunity through induction of perforin and Granzyme B secretion, activation of NK cells and direct killing." (PMID 32328188, 2020). "This system effectively stimulated trafficking of both CD4+ and CD8+ T cells and inhibited tumor growth." (PMID 32440473, 2020). "Co-transplants of HSC with tumor cells in immunocompetent mice inhibited lymphocyte infiltration (CD3-, CD4- and CD8-positive cells) in the tumor, while the immune response was significantly higher when tumors were transplanted without HSC." (PMID 32899119, 2020). "Typically cellular anti-tumour immune responses have been attributed to CD8 T cells; however, we isolated mainly CD4 T cells." (PMID 31915853, 2020). "V-domain Immunoglobulin Suppressor of T cell activation (VISTA; alias PD-1H, Gi24, DD1α, Vsir, or Dies1) is an inhibitory molecule expressed on many cell types including DCs, other myeloid cells, CD4+ and CD8+ T cells as well as tumor cells." (PMID 32674488, 2020). "In contrast, the frequency of circulating CD4+ T cells increased in both AOM/DSS and Emodin groups, relative to tumor free-mice (WT)." (PMID 33489875, 2020). "Recently it was shown that MCPyV TAg-specific CD4+ T cells are enriched in VP-MCC tumors, demonstrating that MCPyV MHC class II restricted TAg epitopes are relevant to tumor immunity." (PMID 33362774, 2020). "Our study also confirms previous studies showing that CD4+ and CD8+ T cells can contribute to anti-neu mAb monotherapy to suppress the growth of the TUBO tumour in WT BALB/c immunocompetent mice." (PMID 32127568, 2020). "In our study, we found that VGLL3 expression positively correlated with tumor heterogeneity regarding immune cell infiltration, particularly with CD8+ T cells, CD4+ T cells, macrophages, neutrophils, and dendritic cells, but not B cells." (PMID 31992826, 2020). "CTLA-4 is also constitutively expressed by the FoxP3+CD4+CD25+ tumor infiltrating regulatory T cells (Tregs), which are important negative regulators of tumor immunity and of autoimmunity." (PMID 32443877, 2020). "Considering T-bet does not appear regulate GzmB expression and the high levels of Prdm1 mRNA observed in CD4+ Th-ctx cells post-αCTLA-4 treatment, we explored whether Blimp-1 contributed to the acquisition of a cytotoxic phenotype by CD4eff T cells and to the overall anti-tumor activity of αCTLA-4." (PMID 31924474, 2020). "In our case, we found increased CD4+ and CD8+ T‐cell infiltration in Y‐27632‐treated tumor, which is consistent with the result of a previous study." (PMID 32941674, 2020). "Given their primary immune function, the monitoring of T-cell populations like CD4 + T, CD8 + T, and the Treg cells and their respective immune function is essential to evaluate the ongoing changes in the tumor microenvironment." (PMID 32805718, 2020). "In tumor tissue, Lsp1-overexpressing CD4+ and CD8+ T cells also showed markedly reduced frequencies of TNF-α+ and/or IFN-γ+ cells compared with WT CD4+ and CD8+ T cells, respectively." (PMID 33020243, 2020). "This is mostly exploding as an acquired immune-paresis of T-cells: Physiologically, when they recognize an antigen on a tumor cell, this is rapidly killed by activated CD8+ cytotoxic T cells, helped by CD4+ T helper cell type 1 (Th1)." (PMID 33255336, 2020). "The mRNA expression data prompted us to stain tumour sections to validate immune-related expression, by which we chose seven immunophenotypical markers [CD45, CD4, CD8, FOXP3, CD79A, Kappa/Lambda (K/L) and SLAMF7] to study both T cell and B cell expression." (PMID 32195184, 2020). "Purified CD4+ DARPin-28z-T cells were generated from a panel of five different PBMC donors and delivered to tumor-bearing NRG mice at equal doses." (PMID 32368616, 2020).
tumor (continued). "DPTs at tumor sites secrete more IL-10, IDO, and TGFβ and express higher levels of immune checkpoints PD-1, LAG-3, and TIM-3 than Tregs, CD4+ T cells and CD8+ T cells." (PMID 32457755, 2020). "By inducing CD4+ and CD8+ T lymphocytes, the MART1/ MART-LAMP1 mRNA lipopolyplex vaccine reduced tumor growth by about 75%." (PMID 32823960, 2020). "Especially, the functional differences between the lower- and higher-grade tumours were remarkable in the CD8+ PD-1highTIM-3− cells and CD4 + PD-1highTIM-3− cells." (PMID 32277125, 2020). "Both types of T lymphocytes CD4+ T helper cells and CD8+ cytotoxic T cells ensure the anti-tumour immune response through inhibiting the occurrence and proliferation of HCC." (PMID 32466214, 2020). "Immunohistochemistry was used to double-stain two adjoining sets of tissue microarrays from pre-RT (radiotherapy) tumour resection samples for CD1a/CD20 and CD45RO/CD4." (PMID 33153211, 2020). "As such, we evaluated the relation between enrichment of T cell markers CD3, CD4, and CD8 at the tumor center versus periphery, and how this relates to attributes of the T cell repertoire." (PMID 32001676, 2020). "In terms of immunosuppressive factors, Treg cells (primarily CD4+ FOXP3+ T lymphocytes) and TAMs (primarily M2 macrophages) are clusters of cells that impede tumor immunity via complex regulation." (PMID 32595757, 2020). "We have shown that expression of MHCII mRNA in clinical samples is correlated with the presence of tumor-infiltrating lymphocytes (TILs) and with elevated expression of TIL genes including CD3D, CD4, and CD8A3." (PMID 32313087, 2020). "In support of this observation, exogenous administration of chemokines following local RT can inhibit tumor growth at distal site, and stimulate infiltration of CD8+ T-, CD4+ T cells, and NK cells." (PMID 32365904, 2020). "This was associated with increased numbers of CD8+ T-cells in tumors, and reduced the number of CD4+ T-cells, the main source of the Th2 cytokine IL4 which can lead to a pro-tumor advantage." (PMID 32656079, 2020). "CD4-GZMA cells and CD8-LAYN cells were found to have higher infiltration in normal tissue while CD8-LEF1 cells showed higher fraction in tumor tissue." (PMID 33043022, 2020). "The frequencies of CD8+ T cells in the peritumor and in the tumor where similar to the PBMC of the same patients; however, the frequencies of CD4+ T cells were similar in both tissues, but lower than in their blood." (PMID 32182707, 2020). "Re-challenge of these PI3KδKI mice, which previously rejected TCL1-leukemia, with tumor cells resulted again in tumor rejection and expansion of CD44+ effector/memory CD4+ as well as CD8+ T-cells." (PMID 33552053, 2020). "No striking differences were observed in the proportion of helper T-cells (CD4+), Foxp3+ T-cells and cytotoxic T-cells (CD8+) among the different treatment groups in the tumor." (PMID 32231867, 2020). "This population assists the generation of Tregs and expresses inhibitory ligands and cytokines (i.e., IL-10), resulting in inhibition of CD4+ and CD8+ T cells and the promotion of tumor growth." (PMID 33255584, 2020). "Western blot showed the anti-PD-1 immunotherapy significantly increased CD4 and CD8 expression in the anti-PD-1-treated tumor group as compared with the IgG-treated tumor group." (PMID 32244307, 2020). "Analyses of 7 GCT specimens showed that 4.0% of total tumor single cells suspensions were CD8+ T cells, 3.3% were CD4+ T cells and 0.72% were CD4+CD25+FOXP3+ Tregs." (PMID 32814714, 2020). "For example, MDSCs promote tumor angiogenesis through vascular endothelial growth factor (VEGF) production and exert their immunosuppressive function through the induction of the CD4(+)CD25(+)Foxp3(+) Tregs." (PMID 33020428, 2020).